APOB (apolipoprotein B)
Diseases named in the same sentence as APOB in open-access papers (continued):
Sharing a sentence is not in itself a finding about the gene and the disease.
dyslipidemia (continued). "Studies have also shown that OSAHS patients are accompanied by dyslipidemia, including significantly increased serum levels of TG, TC, very low-density lipoprotein, LDL, and ApoB, and decreased serum levels of HDL and ApoA levels." (PMID 35923456, 2022). "The high predictive power of Apolipoprotein B and Apolipoprotein B/A1 ratio in CVD and early pre-disease condition, insulin resistance, diabetes, and metabolic syndrome (MS), have been highlighted in several studies." (PMID 34066182, 2021). "Obesity is known to increase the chances of developing dyslipidemia, characterized by elevated plasma triglycerides, reduced high-density lipoprotein (HDL) cholesterol, and elevated apoB concentration." (PMID 34805311, 2021). "In T2DM dyslipidemia presents with a high concentration of free fatty acids and triglycerides, low HDL-c levels and increased sd-LDL particles and ApoB." (PMID 32505210, 2020). "In contrast, CRP was not a significant predictor of cancer death (HR: 0.96; 95% CI 0.54–1.59), after adjustment for traditional risk factors (age, sex, race, alcohol intake, HEI, smoking, BMI, dyslipidemia, HTN, and diabetes) and the apoB/apoA-I ratio." (PMID 31936330, 2020). "Increased sdLDL, along with elevated levels of TRL, LDL cholesterol, oxidized LDL, and apoB and low levels of HDL-chol constitute the ‘atherogenic dyslipidemia complex’, a feature of type 2 diabetes and the metabolic syndrome." (PMID 31247940, 2019). "Compared with control subjects, however, patients with ACS had a higher prevalence of smoking, HTN, diabetes, and dyslipidemia, and lower heart rates, serum cholesterol, HDL, ApoA, and ApoB levels." (PMID 30242056, 2018). "It has been shown that people with excessive visceral fat are exposed to tissue insulin resistance and atherogenic dyslipidemia, with low HDL-C and high concentrations of TG, small dense LDL, and apolipoprotein B." (PMID 30591697, 2018). "Our study confirmed previous reports of the existence of dyslipidemia (enhanced TG, TC, LDL-C, apoB, Lp(a), apoCIII and lower HDL-C and apoAI) and inflammation (increased TNF-α and hs-CRP) in CHD patients." (PMID 30053815, 2018). "The prevalence of dyslipidemia in TC, TG, LDL-C, apoB, and apoE increased with increasing OSA severity (linear trends, p < 0.05)." (PMID 28134311, 2017). "A study assessing aluminium-induced toxicity in a rat model found that melatonin protected against toxic dyslipidemia by alleviating the aluminum induced increases in total cholesterol (TC), LDL-C, TG, oxidized LDL, and apolipoprotein B100 (apoB100)." (PMID 27876064, 2016). "Dyslipidemia is a common feature of T2DM, and quantifiable by the measurement of apolipoprotein B (ApoB) levels." (PMID 27111895, 2016). "In brief, patients with high GS had higher percentage of smoking, hypertension, dyslipidemia and DM, higher level of TC, LDL-C, Lp(a), apoB, fasting blood glucose, hemoglobin A1C (HbA1C), and lower levels of HDL-C, apoA1 and LVEF." (PMID 25426943, 2014). "Although some of these studies have focused on genomic regions that are confirmed to harbor dyslipidemia-predisposing loci, such as APOB, CETP, LIPC and LPL, no exhaustive studies testing whether GWAS-discovered loci modify response to treatments have been previously reported." (PMID 22951888, 2012). "Elevated triglycerides and reduced HDL (i.e., atherogenic dyslipidemia) are usually accompanied by elevated apoB; CRP is a marker of inflammation that tends to be elevated in people with atherosclerotic conditions and metabolic syndrome." (PMID 22814200, 2012).
dyslipidemia (continued). "Rosuvastatin, 10 mg/d administered to patients with the metabolic syndrome, reduced LDL cholesterol by 47%, apolipoprotein B by 37%, and TG by 23%, while increasing HDL cholesterol by 10%." (PMID 22523674, 2012). "Dyslipidemia is less prevalent, however the lipid profile can be considered more 'atherogenic' in MS children, with higher TG, LDL, VLDL and apolipoprotein B, and lower HDL and apolipoprotein A-I." (PMID 20537155, 2010). "Patients with metabolic syndrome and obesity are more likely to have this disparity, which is characterized by elevated ApoB levels without necessarily elevated LDL-C concentrations." (PMID 40379620, 2025). "ApoB can also serve as an important target for the prevention and treatment of ASCVD, particularly in patients with mild to moderate hypertriglyceridemia (2–5.6 mmol/L), diabetes, obesity, or metabolic syndrome, or in patients with LDL-C levels < 1.8 mmol/L." (PMID 40775270, 2025). "Dyslipidemia associated with obesity typically includes elevated levels of TGs, very-low-density lipoproteins (VLDL), apolipoprotein B (apoB), and non-HDL-C, combined with decreased HDL-C and apolipoprotein A-I (apoA-I)." (PMID 41003008, 2025). "According to the TG and ApoB/A1 definitions, the ORs for dyslipidemia was not statistically significant in the female population." (PMID 39170735, 2024). "Dyslipidemia, such as higher leves of total cholesterol (TC), triglycerides (TG), low-density lipoprotein-cholesterol (LDL-C), and apolipoprotein B (ApoB), may enhance the likelihood of colorectal polyps formation." (PMID 39252808, 2024). "The ApoB:ApoA1 ratio is an effective biomarker for predicting metabolic syndrome and coronary artery disease independent of LDL and HDL cholesterol markers." (PMID 38609170, 2024). "The MD was −4.14 (95% CI: −11.32 to 3.05; p = 0.26), demonstrating that a 4 mg dose of saroglitazar did not affect the apolipoprotein B level compared to that in the control group in patients with dyslipidemia." (PMID 37685742, 2023). "This meta-analysis suggests that 4 mg of saroglitazar reduces triglyceride, LDL-C, and total cholesterol levels in patients with dyslipidemia; however, there were no significant changes in apolipoprotein B levels." (PMID 37685742, 2023). "On the other hand, the last patient, a carrier of APOB c.5600G>A, had dyslipidemia without any other known personal or family history suggestive of FH." (PMID 36769882, 2023). "In Brazil, 83.3% of the patients with JIA demonstrated dyslipidemia based on the TC, HDLc, LDLc, TG, non-HDLc, apolipoprotein A1 (ApoA1), and apolipoprotein B (ApoB) concentrations." (PMID 36832332, 2023). "Many genes such as APOB, LPL, APOA1, LEP, CD36, IL-6, and APOE may play an important role in dyslipidemia." (PMID 36061816, 2022). "Patients with diabetes mellitus, obesity or metabolic syndrome have a residual lipid risk, which can be captured by non-HDL-C and ApoB measurements." (PMID 36498823, 2022). "The ESC recommends non-HDL-C and ApoB measurements in all individuals with high TG levels, diabetes mellitus, obesity and metabolic syndrome." (PMID 36498823, 2022). "In general, dyslipidemia is characterized by high circulating concentrations of low-density lipoprotein-cholesterol (LDL-C), triglycerides (TGs), and apolipoprotein B (ApoB); and low circulating concentrations of high-density lipoprotein-cholesterol (HDL-C) and apolipoprotein A1 (ApoA1)." (PMID 36545018, 2022). "These local series of studies show that dyslipidemia causing arteriosclerosis, including TC/HDL-C ratio, lower HDL-C value, higher ApoB, and Non-HDL-C values, are important lipid factors for coronary artery heart disease in Taiwan residents." (PMID 35203576, 2022).
dyslipidemia (continued). "Abundant data have shown that evolocumab intensely reduces LDL-C, non-HDL-C, ApoB, Lp(a), and remnant cholesterol in subjects with T2D with and without atherogenic dyslipidemia." (PMID 35933413, 2022). "Next, MACCE and follow-up time were the dependent variables, while age, BMI, smoking, hypertension, dyslipidemia, SBP, DBP, FPG, HbA1c, insulin, TG, TC, HDL-C, LDL-C, sdIDL-C, ApoA-I, ApoB, Lp(a), hsCRP, neutrophils, Scr, UA, and NGAL were set as independent variables." (PMID 36397150, 2022). "In consistent, our MS-stratified analysis showed an impaired anti-inflammatory capacity of apoB-depleted plasma in metabolic syndrome subjects compared to non-MS subjects." (PMID 35413066, 2022). "The most encountered lipid abnormalities in type 2 diabetes are atherogenic dyslipidemia, including increased TG, apolipoprotein B, non-HDL-C, and decreased HDL-C." (PMID 36286294, 2022). "On the other hand, when TG > 1.5 mmol/L, the Canadian Cardiovascular Society dyslipidemia guidelines recommend using non-HDL-C or apolipoprotein B level as the preferred alternatives to LDL-C level." (PMID 36700190, 2022). "Model 1 including Glucose, HbA1c, LDL-C, Non-HDL-C, sdLDL-C, ApoA-I and ApoB and Model 2 only including sdLDL-C and HbA1c showed that just sdLDL-C and HbA1c remained significantly associated with the risk of CVs These results suggest that elevated Glucose and dyslipidemia might contribute to CVs." (PMID 33910639, 2021). "Recently, non-High-Density Lipoprotein-Cholesterol (non-HDL-C), Apolipoprotein B (ApoB) and remnant-Cholesterol (remnant-C) have been suggested as better biomarkers for dyslipidemia." (PMID 33879161, 2021). "Elevated plasma BCAA were also associated with an unfavorable fasting blood lipid profile in our subjects, including higher TG, LDL-C and ApoB/ApoA1 ratio and lower HDL-C, consistent with the BCAA-dyslipidemia links established in Asian and Caucasian populations." (PMID 33996878, 2021). "The previous study using the same cohort confirmed positive correlations of SF with dyslipidemia and unfavorable lipid ratios, especially apoB and non-HDL-C, independent of HOMA-IR." (PMID 33659229, 2021). "The relative abundance of the Christensenellaceae family has a negative relationship with BMI, LDL, and apolipoprotein B as well as features of metabolic syndrome such as obesity and hypertriglyceridemia, and was positively associated with HDL." (PMID 34041041, 2021). "As expected, subjects with mixed dyslipidemia had higher values of apolipoprotein B, non-HDL cholesterol, LDL-C and VLDL-C (P < 0.001)." (PMID 33952259, 2021). "Concomitant dyslipidemia has a particular pattern characterized by a high flux of free fatty acids, hypertriglyceridemia, low HDL-c values, increased sd-LDL particles and high ApoB values." (PMID 31409878, 2019). "Insulin resistant cardiometabolic disease often entails an ‘atherogenic dyslipidemia’, characterized by elevated plasma TG, low HDL-C levels, a preponderance of small, dense LDL particles, and elevated apolipoproteins (apo) B (apoB 100 and apoB48) and C-III concentrations." (PMID 31164165, 2019). "Our results show that the pro-atherogenic lipid profile characteristic of women with severe obesity and the metabolic syndrome turns into a healthier one after bariatric surgery, with a significant increase in HDL and ApoA1, and a decrease in LDL, oxLDL and ApoB." (PMID 29925393, 2018). "However, the NLA emphasizes therelevance of atherogenic dyslipidemia and the Canadian guidelines introducednon-HDL-C and apolipoprotein B as alternative targets." (PMID 28699976, 2017).
dyslipidemia (continued). "Thus, despite LDL cholesterol levels being grossly similar, subjects with insulin resistance, metabolic syndrome, type 2 diabetes, and CVD had higher levels of apoB compared with healthy subjects." (PMID 28830468, 2017). "Males had significantly higher prevalence of high LDL-C, high non-HDL-C, high ApoB and mixed dyslipidemia than females, while other lipid parameters were similar." (PMID 28376848, 2017). "Although the precise mechanism whereby obesity results in dyslipidemia has not been established, there is some evidence to support that visceral obesity is related to dysregulation of both apoB isoforms." (PMID 26451733, 2015). "In our study, TG/HDL and LDL/HDL, which are considered as a better predictor of metabolic syndrome and insulin resistance than apolipoprotein B/apolipoprotein A1, were negatively correlated with QUICKI, indicating the close relationship between dyslipidemia and IR." (PMID 24391852, 2013). "The apoB:apoA1 ratio was found to predict metabolic syndrome in nonobese but not obese participants, perhaps because obese participants are more likely to have diabetes." (PMID 21159217, 2011). "In this study involving diabetic patients, apoB did not perform significantly better than non-HDL-C to rank patients according to atherogenic dyslipidemia." (PMID 21356116, 2011). "Non-HDL-C and ApoB are particularly informative in patients with hypertriglyceridemia, mixed dyslipidemia, type 2 diabetes, or metabolic syndrome, and they are also useful for identifying phenotypes such as type III hyperlipoproteinemia or high‐risk normotriglyceridemic hyperapoB individuals." (PMID 41388300, 2025). "Dyslipidemia in cholestasis is defined by the presence of lipoprotein X (Lp-X), a biliary lipoprotein complex characterized by a predominance of albumin and absence of apolipoprotein B (apoB)." (PMID 40465020, 2025). "Dyslipidemia is characterized by aberrant levels of circulating lipids and apolipoproteins, including total cholesterol (TC), triglycerides (TG), high-density lipoprotein cholesterol (HDL-C), low-density lipoprotein cholesterol (LDL-C), apolipoprotein A1 (ApoA1), and apolipoprotein B (ApoB)." (PMID 41430991, 2025). "Dyslipidemias are often diagnosed based on an individual’s lipid panel that may or may not include Lp(a) or apoB." (PMID 40004987, 2025). "Notably, 65-95% of PCOS patients manifested IR with compensatory hyperinsulinemia, and those with concurrent IR exhibit atherogenic dyslipidemia characterized by elevated TG, LDL, ApoB, TG/HDL, and ApoB/ApoA ratio, with TG and ApoB levels exhibiting positive correlation with BMI." (PMID 41040863, 2025). "In a phase 2 clinical trial involving 364 patients with mild dyslipidemia (TULIP), the prescription of obicetrapib at doses ranging from 1 to 10 mg for 12 weeks, both alone and in combination with moderate-intensity statins, showed favorable outcomes in ApoB concentrations." (PMID 38393015, 2024). "Dyslipidemia is a prominent metabolic disease characterized by abnormal changes in lipids including high-density lipoprotein (HDL) cholesterol, low-density lipoprotein (LDL) cholesterol, total cholesterol (TC), triglyceride (TG), apolipoprotein A-I (APOA1), and apolipoprotein B (APOB)." (PMID 39857597, 2024). "Our findings indicate that PS supplementation substantially reduced total TC, LDL-c, and ApoB while concurrently enhancing HDL-c across the entire population, encompassing both healthy individuals and those with hypercholesterolemia, hypertension, and metabolic syndrome." (PMID 39432657, 2024). "An analysis of the Women’s Health Study cohortinvolving female healthcare professionals revealed that in women under 55 yearsof age, premature CAD was more closely associated with diabetes mellitus,metabolic syndrome, hypertension, and smoking than LDL-C, non-HDL-C, and ApoB." (PMID 39228502, 2024).
dyslipidemia (continued). "Some researchers have indicated that the ApoB/ApoA-I ratio is the strongest indicator of the risk of CVD and may be particularly useful in assessing its risk in metabolic syndrome, even when concentrations of LDL are generally not elevated." (PMID 35955978, 2022). "Dyslipidemia is the major constituent of MetS, characterized by raised free fatty acids (FFAs), TG, small dense low-density lipoprotein cholesterol (LDL-C) and apolipoprotein B (apoB) levels, but low HDL cholesterol level." (PMID 36551995, 2022). "Non-HDL-C and apolipoprotein B (ApoB) are the preferred therapeutic targets for mixed dyslipidemia." (PMID 32035487, 2020). "The systemic inflammation state in NAFLD patients could further enhance the presence of atherogenic dyslipidemia (an increase in LDL-c, TG, and apolipoprotein B and decrease in HDL) and increased carotid intima-media thickness, resulting in more CVE in these individuals." (PMID 32327942, 2020). "Second, patients with PE often develop dyslipidemia, with increased levels of serum triglyceride, decreased levels of high-density lipoprotein (HDL), reduced sizes of low-density lipoprotein (LDL), and a reduced ratio of LDL cholesterol to apolipoprotein B (LDLc–apo B) in the third trimester." (PMID 33212799, 2020). "In 2019, the ESC/EAS Guidelines recommended that, when evaluating patients with diabetes, metabolic syndrome, obesity, high triglyceride concentration or very low LDL-c levels, non-HDL and ApoB could be preferred in order to estimate CV risk." (PMID 32505210, 2020). "Furthermore, the components of dyslipidemia may differ between genders, e.g., males showed higher TG, LDL, and apoB and lower HDL, apoA-I, and apoE than females." (PMID 31093507, 2019). "This atherogenic dyslipidemia consists of an excess of atherogenic apolipoprotein B (ApoB)-containing lipoproteins, which is reflected by higher circulating ApoB, non-high-density lipoprotein cholesterol (non-HDL-C), and low-density lipoprotein particle number (LDL-PN)." (PMID 31706300, 2019). "We further observed moderate to strong correlation of primary lipid parameters such as TC, HDL-C, and LDL-C with derived or secondary lipid parameters such as TC/HDL-C ratio, non-HDL-C and ApoB which are regarded as better predictors of insulin resistance, metabolic syndrome and CVDs." (PMID 28376848, 2017). "In this double blind, placebo controlled randomized trial in people with metabolic syndrome, daily consumption of a food supplement combining RYR and olive fruit extract resulted in a 24% decrease of LDL concentrations, accompanied by a smaller but significant decrease of total CHOL, apoB, and TG." (PMID 25879228, 2015). "Second, we did not check the specific lipoproteins related to atherogenic dyslipidemia such as apolipoprotein B, which may be more specific to LDL particles." (PMID 25761189, 2015). "It remains unclear whether apoB/apoA1 ratio is a better indicator for identifying metabolic syndrome in the Chinese population, and there are no optimal cut-off values of apoB/apoA1 ratio for Chinese men and women yet." (PMID 24886173, 2014). "The prevalence of diabetes and hypertension is elevated and often underrecognized, and dyslipidemia patterns are that of lower LDL-C, higher triglycerides, and lower high-density lipoprotein cholesterol (HDL-C), emphasizing the importance of non-HDL-C and ApoB in risk assessment." (PMID 40579058, 2025). "Instead, apoB or non-HDL-C are endorsed as practical surrogate markers for assessing total atherogenic particle burden, particularly in patients with elevated triglycerides, metabolic syndrome, type 2 diabetes, or obesity, all of which are associated with increased sdLDL concentrations." (PMID 40725639, 2025). "In addition, we will focus on future directions of lipid-lowering agents and whether or not apoB should play a more central role in controlling and monitoring dyslipidemia." (PMID 34677405, 2021).